UBE2C (ubiquitin conjugating enzyme E2 C)
Diseases named in the same sentence as UBE2C in open-access papers (continued):
Sharing a sentence is not in itself a finding about the gene and the disease.
head and neck squamous cell carcinoma (10 papers, 2020 to 2024). A squamous cell carcinoma that arises from any of the following anatomic sites: lip and oral cavity, nasal cavity, paranasal sinuses, pharynx, larynx, and salivary glands. "Zhenning Jin and colleagues indicated that UBE2C was upregulated in head and neck squamous cell carcinoma, and downregulation of UBE2C significantly suppressed cell migration and cell invasion." (PMID 38102624, 2023). "For example, CPSF1 promotes head and neck squamous cell carcinoma growth by regulating AS in cancer-associated genes, such as AKT2, HRAS, TGFBI, and UBE2C." (PMID 33748106, 2021). "Notably, all patients with UCS, OV, ESCA, CESC, and head and neck squamous cell carcinoma (HNSC) had amplification of the UBE2C gene, which showed an alteration frequency of ~7%, ~4%, ~3%, ~2%, and ~1%, respectively." (PMID 38577722, 2024). "Yanget al. reported that UBE2C could trigger HIF-1alpha-glycolytic flux in head and neck squamous cell carcinomas, suggesting a close link between UBE2C and aerobic glycolysis." (PMID 38634120, 2024).
pancreatic cancer (9 papers, 2019 to 2024). "The mRNA and/or protein levels of UBE2C are aberrantly enhanced in pancreatic cancer with dismal clinical outcomes." (PMID 37540295, 2023). "The dysregulation of UBE2C is related with the proliferation of cancer cells and poor overall survival in pancreatic carcinoma." (PMID 35563183, 2022). "As we expected, UBE2C is positively correlated with bladder cancer progression as well as renal cell carcinoma, pancreatic cancer." (PMID 33630978, 2021). "A previous study reported that UBE2C could promote the progression of pancreatic cancer through the PI3K/AKT signaling pathway." (PMID 38637730, 2024).
bladder cancer (8 papers, 2014 to 2024). "Using high-throughput sequencing, we found that ubiquitin-conjugating enzyme E2 C (UBE2C) was overexpressed in bladder cancer (BCa) and was strongly associated with an unfavorable prognosis." (PMID 38949026, 2024). "In this study, we demonstrated that ubiquitin-conjugating enzyme E2 C (UBE2C) was upregulated in bladder cancer (BCa) and was positively associated with lymphangiogenesis and LN metastasis." (PMID 38949026, 2024). "UBE2C mediates crosstalk between the monoubiquitination and K63-linked polyubiquitination of SNAT2 to promote bladder cancer lymphatic metastasis." (PMID 38949026, 2024). "Among them, TOP2A, CDC20, CDCA5 and UBE2C all act as oncogenes in bladder cancer and promote tumor progression." (PMID 36932399, 2023). "UBE2C expression was positively correlated with unfavorable overall survival in ovarian and bladder cancers." (PMID 32899896, 2020). "Likewise, our finding showed that the missense mutation is the major type of UBE2C mutation that happens in COAD, UCEC, bladder carcinoma and sarcoma." (PMID 38577722, 2024).
nasopharyngeal carcinoma (8 papers, 2013 to 2024). A carcinoma arising from the nasopharyngeal epithelium. "In addition, UBE2C might be involved in B cell receptor signaling pathways and other functions associated with immune system activation in nasopharyngeal carcinoma." (PMID 34950739, 2021). "The results of proteomic and transcriptomic studies indicate that there is a significant correlation between nasopharyngeal carcinoma and ubiquitinated proteins, which indicates that UBE2C plays a key role in nasopharyngeal carcinoma." (PMID 39334908, 2024). "In additionally, knockdown UBE2C expression attenuated cell proliferation and induced cell cycle arrest of S and G2/M phases in nasopharyngeal carcinoma cells." (PMID 38102624, 2023). "However, the role of UBE2C in human nasopharyngeal carcinoma (NPC) is unclear." (PMID 23587173, 2013). "In this study, UBE2C, as a downstream gene of NCL/EBNA1, played a central role in the invasion and metastasis of nasopharyngeal carcinoma." (PMID 39334908, 2024). "In vitro studies further validated the function of the key targets, suggesting that UBE2C plays an important role in NCL and EBNA1-mediated curcumol resistance to nasopharyngeal carcinoma invasion and metastasis." (PMID 39334908, 2024). "UBE2C promotes the progression of HNSCC and nasopharyngeal carcinoma progression." (PMID 32899896, 2020).
COVID-19 (6 papers, 2022 to 2025). A disease caused by infection with severe acute respiratory syndrome coronavirus 2. "The GSE167028 and GSE150392 datasets were subjected to a recent bioinformatic analysis, which unveiled six critical genes (CDK1, KIF20A, PBK, KIF2C, CDC20, and UBE2C) associated with COVID-19 myocarditis." (PMID 40230577, 2025). "In influenza, UBE2S, USP53, and TIMM10 were observed in this category, while in COVID-19, UBE2T, UBE2C, DTL, MT-ND2, UCHL1, and UBA52 were implicated." (PMID 41020849, 2025). "Geldanamycin has also been observed to downregulate the expression of the cell cycle genes CCNB1 and UBE2C in COVID-19, which can potentially serve as effective antiviral and anti-inflammatory agents." (PMID 38932215, 2024). "In a COVID-19 patient, helveticoside has been found to downregulate UBE2C expression, leading to the inhibition of viral proliferation and apoptosis." (PMID 38932215, 2024). "Eventually, 6 genes (CDK1, KIF20A, PBK, KIF2C, CDC20, UBE2C) were identified by CytoHubba plug-in of Cytoscape as critical genes of COVID-19 Myocarditis for future study." (PMID 35749386, 2022). "Based on 5 algorithms of the CytoHubba plug-in, six genes (CDK1, KIF20A, PBK, KIF2C, CDC20, UBE2C) were confirmed as critical genes related to COVID-19 Myocarditis." (PMID 35749386, 2022). "Based on topological algorithms (i.e., degree), in this study, CDK1, KIF20A, PBK, KIF2C, CDC20, and UBE2C were identified as critical genes that may be potential biomarkers for COVID-19 Myocarditis." (PMID 35749386, 2022). "It is worth highlighting that critical genes (CDK1, KIF20A, PBK, KIF2C, CDC20, UBE2C) may be potential biomarkers and treatment targets of COVID-19 Myocarditis for future study." (PMID 35749386, 2022).
esophageal cancer (6 papers, 2013 to 2024). A primary or metastatic malignant neoplasm involving the esophagus. "UBE2C is highly expressed in esophageal cancer and is associated with poor prognosis, which may be related to the mechanism of drug resistance to masitinib." (PMID 35568702, 2022). "One of the numerous potential molecular mechanisms underlying esophageal cancer may involve ubiquitin conjugating enzyme E2 C (UBE2C), a protein-coding gene related to pathways such as the cell cycle and mitosis that modulate the progression of cancer." (PMID 34488675, 2021). "The differential expression of UBE2C in esophageal cancer and adjacent cancer makes it a reliable index for the diagnosis of the EC." (PMID 35568702, 2022). "Subsequent statistical analysis found that the expression of UBE2C in esophageal cancer tissues was higher than that in adjacent tissues." (PMID 35568702, 2022). "In immunohistochemical analysis, UBE2C was strongly expressed in esophageal cancer tissues and negatively expressed in adjacent tissues." (PMID 35568702, 2022). "ROC curve results showed that UBE2C had a good differential diagnosis ability for esophageal cancer." (PMID 35568702, 2022). "The cell cycle regulator FOXM1 binds to the UBE2C promoter region in esophageal cancer cells and activates its transcription, leading to upregulation of UBE2C expression." (PMID 33810518, 2021). "The copy number analysis of UBE2C in the esophageal cancer dataset showed that UBE2C was amplified in 32 (6%) of 559 cases." (PMID 34488675, 2021). "Pathway anaylsis showed that UBE2C mainly influenced the biological function of esophageal cancer by synergistic effects with CDK1, PTTG1 and SKP2." (PMID 34488675, 2021). "The PPI results of the first five KEGG pathway proteins showed that UBE2C mainly influenced the biological function of esophageal cancer by synergistic effects with CDK1, PTTG1, and SKP2 (all three are involved in the cell cycle pathway)." (PMID 34488675, 2021). "These in vitro results were also consistent with other reports that targeting UBE2C may be a useful therapeutic strategy in various cancers, such as cervical, colorectal and esophageal carcinomas." (PMID 23587173, 2013). "UBE2C and APC/C affect the proliferation rate and cell cycle distribution of esophageal cancer cells by interfering with the level of CCNB." (PMID 33810518, 2021). "Another in vitro study confirmed that UBE2C knockdown significantly inhibited proliferation and induced apoptosis of the TE1 esophageal cancer cell line." (PMID 34488675, 2021).
lung squamous cell carcinoma (6 papers, 2020 to 2023). "The average expression level of UBE2C was higher in large cell lung cancer and SCLC, while the expression level was lower in normal, LUAD, and squamous cell lung cancer tissues." (PMID 37583423, 2023).
rectal carcinoma (6 papers, 2019 to 2023). A malignant epithelial neoplasm that arises from the rectum and invades through the muscularis mucosa into the submucosa. "Rectal cancer with overexpressed UBE2C regulates miR-381 expression, encouraging rectal carcinoma cell proliferation and invasion." (PMID 37457582, 2023). "Over-expressed of UBE2C in rectal carcinoma modulates miR-381 expression, promoting proliferation invasion of rectal carcinoma cells but inhibits apoptosis of cells." (PMID 34907282, 2021). "In vivo, a study in a xenograft mouse model showed that UBE2C promotes tumor growth, suggesting that UBE2C promotes cell proliferation, in rectal carcinoma." (PMID 33324542, 2020). "In addition, it was found that UBE2C knockdown leads to the reduction of anchorage-independent growth of rectal carcinoma cells and that UBE2C is targeted by miR-381, suggesting that miR-381 can modulate anchorage-independent growth partly via UBE2C." (PMID 33435156, 2021). "In addition, UBE2C is more highly expressed in rectal carcinoma tissues than in the corresponding non-cancerous tissues and promotes cell proliferation and invasion." (PMID 33324542, 2020).
breast tumor (5 papers, 2014 to 2025). "The relative gene expression analysis of seven PGC-associated genes, including CCNB1, CCNB2, FEN1, MCM4, PTTG1, RACGAP1, and UBE2C, was conducted on the samples of breast tumors compared to healthy mammary tissues." (PMID 41009526, 2025). "Through integrative analyses of transcriptomic datasets, we identified a germline-associated molecular signature, with CCNB1, CCNB2, PTTG1, RACGAP1, and UBE2C emerging as core EGT gene clusters markedly upregulated in breast tumors." (PMID 41009526, 2025). "The result of our experience has highlighted a significant overexpression of five CCNB1, CCNB2, PTTG1, RACGAP1, and UBE2C genes in breast tumors compared to the normal tissues (p-value < 0.05)." (PMID 41009526, 2025). "In conclusion, UBE2S and UBE2C both inhibited Numb expression and promoted breast tumor malignancy." (PMID 36860312, 2023). "We found that UBE2C expression was associated with the expression of the tumor initiator HER2, and MC lesions with high mRNA expression of HER-2 also showed high mRNA expression of UBE2C in breast core biopsies, which is consistent with previous observations in breast tumor tissue and cells." (PMID 24699941, 2014). "Significantly increased mRNA levels were found in breast tumors compared to healthy controls for UBE2T, UBE2C, BIRC5, TCEB2." (PMID 33671201, 2021). "We determined the expression of the common breast tumor markers HER2, ER and PR in MC biopsies with IDC by immunohistochemistry and then analyzed the fold induction of UBE2C." (PMID 24699941, 2014). "The average expressions of these genes in breast tumor samples compared to healthy mammary biopsies (tumor/healthy) were as follows: CCNB2 (0.483/−0.869), CCNB1 (0.262/−0.472), PTTG1 (0.398/−0.719), RACGAP1 (0.338/−0.609), and UBE2C (0.565/−1.016)." (PMID 41009526, 2025). "In addition, 6/7 PC-CIN genes (CEP55, UBE2C, MELK, TPX2, PTTG1, and CDCA3) were also found to be among the top DEGs identified through comparison of high aneuploidy versus low aneuploidy breast tumors in TCGA." (PMID 32380981, 2020).
clear cell renal cell carcinoma (5 papers, 2020 to 2025). "One study by Yongwen (2019) identified 9 key genes in clear cell renal cell carcinoma, which including UBE2C and CDC20." (PMID 36385010, 2022). "Consistent with the literature, CDC20 was coexpressed with UBE2C in human clear cell renal cell carcinoma." (PMID 35804892, 2022).
esophageal adenocarcinoma (5 papers, 2016 to 2025). A malignant tumor with glandular differentiation arising predominantly from Barrett mucosa in the lower third of the esophagus. "Moreover, UBE2C overexpression has been associated with decreased survival rates of the patients in a wide range of tumors, including the esophageal adenocarcinoma." (PMID 27588470, 2016). "High expression of UBE2C and sensitivity of tumor cells after silencing UBE2C were also detected in esophageal adenocarcinoma." (PMID 39944135, 2025). "In esophageal adenocarcinoma (EA), the expression of UBE2C was elevated compared to Barrett's metaplasia, and was suppressed by proteasome inhibition, resulting in suppressed cell proliferation and cell cycle." (PMID 27556859, 2016). "Recently, a positive correlation between UBE2C and FOXM1 gene expression in esophageal adenocarcinoma (EAC) samples and in vitro EAC-derived cells was reported." (PMID 29596365, 2018).
glioblastoma (5 papers, 2020 to 2026). The most malignant astrocytic tumor (WHO grade IV). "High expression of the E2 conjugase UBE2C is associated with several aggressive cancers, including glioblastoma and we can now include the ST_EPN_RELA subtype as well." (PMID 36293188, 2022). "Using a scoring system combining intensity and frequency of UBE2C staining, we have observed that most BM samples (55%) have high levels of UBE2C (Score III and IV), in contrast with glioblastomas in which 70% of the samples have low expression of this protein." (PMID 37215954, 2023). "This suggests that high UBE2C expression is a feature of brain metastatic tumors, but not of primary brain tumors, such as glioblastoma." (PMID 37215954, 2023).
lymph node metastasis (5 papers, 2017 to 2023). "Our results indicated that UBE2C was involved in cell invasion and migration in OSCC cells; higher UBE2C expression was associated with lymph node metastasis in OSCC patients and with poor DSS in TSCC patients having lymph node metastasis." (PMID 32899896, 2020). "Furthermore, a high expression level of UBE2C was associated with shorter DSS in TSCC patients with poor cell differentiation (p = 0.042), advanced pathological stage (p = 0.001), lymph node metastasis (p = 0.041) and postoperative radiation therapy (p = 0.002)." (PMID 32899896, 2020). "By log rank test, we found that OSCC patients with high UBE2C level had a significantly shorter DSS, especially for those with advanced pathological stage (p < 0.001) and lymph node metastasis (p = 0.019)." (PMID 32899896, 2020). "UBE2C expression in BRCA was significantly related to histological grade, tumor size, lymph node metastasis and clinical stage (P < 0.05)." (PMID 29021715, 2017). "Expression of UBE2C was significantly related to tumor stages, lymph node metastasis (LNM), and FIGO stages, but not to patients age, smoking and alcohol status, gross type, and tumor diameter." (PMID 37335710, 2023). "Remarkably, increased UBE2C expression promotes chromosomal instability, cell cycle progression, proliferation and EMT, being positively correlated with worse clinical outcomes, mainly overall survival, lymph node metastasis, and progression-free survival." (PMID 32183400, 2020). "High UBE2C expression was also correlated with shorter disease-specific survival in TSCC patients having poor cell differentiation, advanced pathological stages, lymph node metastasis as well as receiving radiation therapy." (PMID 32899896, 2020).
lymphoma (5 papers, 2014 to 2024). A malignant (clonal) proliferation of B- lymphocytes or T- lymphocytes which involves the lymph nodes, bone marrow and/or extranodal sites. "In particular, UBE2C expression correlates with lymphoma aggressiveness." (PMID 32674429, 2020).
meningioma (5 papers, 2016 to 2024). A generally slow growing tumor attached to the dura mater. "When exploring UBE2C function in meningioma cells with different grades, it was reported that silencing this gene inhibits proliferation, migration, and invasion." (PMID 37958776, 2023). "In meningiomas, UBE2C overexpression correlates with higher histological grade, increased proliferation, and poor prognosis." (PMID 37958776, 2023). "High expression levels of UBE2C were correlated with high rates of tumor recurrence in meningiomas." (PMID 32899896, 2020). "In WHO°II meningiomas reduced expression of LEPR and MN1 resulted in a significantly shorter PFS, while in WHO°III meningiomas this was the case for a higher expression levels of PTTG1 and UBE2C." (PMID 26894859, 2016). "In accordance with our findings, the remaining four top genes were previously found to be either upregulated (UBE2C and PRC1) or downregulated (LEPR and MN1) in WHO grade II and III meningiomas." (PMID 26894859, 2016).
sarcoma (5 papers, 2020 to 2024). A usually aggressive malignant neoplasm of the soft tissue or bone. "As prior work already has validated asparagine starvation as an actionable metabolic vulnerability in sarcomas, this study concentrates on the potential roles of UBE2C, CENPE, HAS2 and CREB3L2 in STS with a focus on RMS." (PMID 32898143, 2020). "Given that downregulation of Ube2c, Cenpe, Has2 and Creb3l2 by shRNA knockdown diminished mouse sarcoma cell proliferation in vitro, we hypothesized that small molecule inhibitors previously reported to impede the cellular functions of these targets could prove useful in inhibiting their growth." (PMID 32898143, 2020). "Increased expression of UBE2C, CENPE and CREB3L2 compared to normal muscle was detected in 9 of 9 human sarcoma cell lines analyzed, whereas HAS2 expression was detected in only 5 of 9 human sarcoma lines." (PMID 32898143, 2020).
squamous cell carcinoma (5 papers, 2019 to 2025). A carcinoma arising from squamous epithelial cells. "Other key genes, such as CDC20, CCNB1, CHK1, and UBE2C, are well-known regulators of mitotic progression and therapeutic resistance in squamous carcinomas." (PMID 41323280, 2025). "The expression levels of UBE2C were examined by immunohistochemistry in 185 buccal mucosa squamous cell carcinomas, 247 tongue squamous cell carcinomas (TSCCs) and 75 lip squamous cell carcinomas." (PMID 32899896, 2020). "In ESCA, UBE2C expression was increased in both subtypes, including adenocarcinoma and squamous-cell-carcinoma." (PMID 31067633, 2019). "Tongue squamous cell carcinoma cells with UBE2C silencing exhibit lowered expression of the cancer stemness markers ALDH1/A2, CD44, CD166 and EpCAM, indicating the role of UBE2C in controlling the cancer stemness." (PMID 36551544, 2022).
tongue squamous cell carcinoma (5 papers, 2020 to 2024). A squamous cell carcinoma that arises from the tongue. "In the study by Bor-Hwang Kang, UBE2C was reported to be a potential biomarker for the occurrence and prognosis of tongue squamous cell carcinoma." (PMID 39234248, 2024). "However, previous studies showed that UBE2C was upregulated in HNSCC patients and its expression was associated with lymph node metastasis in tongue squamous cell carcinoma patients." (PMID 35615976, 2022).